PLIN2 (perilipin 2)
Diseases named in the same sentence as PLIN2 in open-access papers (continued):
Sharing a sentence is not in itself a finding about the gene and the disease.
pulmonary fibrosis (3 papers, 2017 to 2025). Chronic progressive interstitial lung disorder characterized by the replacement of the lung tissue by connective tissue, leading to progressive dyspnea, respiratory failure, or right heart failure. "The interstitial regions of the lungs express PLIN2+, responsible for phospholipid storage, a subset which are also elevated in pulmonary fibrosis." (PMID 36926329, 2023). "Lung fibroblasts from control subjects consist primarily of fibroblast and myofibroblast populations, while lung fibroblasts from patients with pulmonary fibrosis are characterized by expansion of the myofibroblast population and appearance of PLIN2+ and HAS1High populations." (PMID 40454944, 2025).
Sepsis (3 papers, 2017 to 2022). Sepsis is defined as life-threatening organ dysfunction caused by a dysregulated host response to infection. "We measured serum PLIN2 serum in 259 critically ill patients (166 with sepsis) upon admission to a medical intensive care unit (ICU) compared to 12 healthy controls." (PMID 34572396, 2021). "For indicating sepsis, PLIN2 serum levels above the median had a sensitivity of 55.4%, a specificity of 58.1%, a positive predictive value (PPV) of 70.2% and a negative predictive value (NPV) of 42.2%." (PMID 34572396, 2021). "In general, the conclusions drawn from these reports are consistent with the results in our research, that is, Hmox1, Epas1, Sirt1, Slc3a2, Jun, Plin2 and Zfp36 collectively promote the development of sepsis-induced liver failure by interacting with B cells and NK cells." (PMID 35923893, 2022). "Therefore, we screened the ferroptosis-related genes (Hmox1, Epas1, Sirt1, Slc3a2, Jun, Plin2 and Zfp36) in this study through bioinformatics analysis, and found that these genes were highly expressed in sepsis-induced liver failure model." (PMID 35923893, 2022). "Another restriction is that the observed association of serum PLIN2 with sepsis was rather weak and does not appear to be clinically meaningful." (PMID 34572396, 2021). "We performed uni- and multivariable logistic regression analyses to evaluate whether PLIN2 acts as an independent marker for occurrence of sepsis and disease severity (i.e., multiple organ dysfunction (MOD))." (PMID 34572396, 2021). "Because sepsis was a main cause for admission to our medical ICU, we assessed whether PLIN2 levels were associated with sepsis occurrence." (PMID 34572396, 2021). "However, no assessment currently exists of PLIN2 in critically ill patients and sepsis." (PMID 34572396, 2021).
acne (2 papers, 2023 to 2024). An inflammatory process of the sebaceous glands which is characterized by comedones, nodules, papules and/or pustules on the skin. "The experimental results demonstrated that PLIN2 was more intensely expressed in the acne-like ear skin lesions." (PMID 38792208, 2024). "However, GA treatment obviously reduced the expression level of PLIN2 in the P. acnes-induced acne-like ear skin lesions in a concentration-dependent manner." (PMID 38792208, 2024). "The aim of this study was to see whether levels of perilipin 2 and MC5‐Rs correlate with the development of acne vulgaris." (PMID 37275429, 2023).
arterial hypertension (2 papers, 2021 to 2025). "Intrigued by these findings, we investigated whether arterial hypertension or coronary artery disease are associated with altered PLIN2 serum levels." (PMID 34572396, 2021).
atrial fibrillation (2 papers, 2025). A disorder characterized by an electrocardiographic finding of a supraventricular arrhythmia characterized by the replacement of consistent P waves by rapid oscillations or fibrillatory waves that vary in size, shape and timing and are accompanied by an irregular ventricular response. "Our proteomics analysis detected increased expression of the LD-associated protein Plin2, whose upregulation has been implicated in atrial sclerosis and atrial fibrillation 38, in the cardiac tissue of our SACI mouse model." (PMID 40963918, 2025).
brain ischemia (2 papers, 2023). Diminished or absent blood supply to the brain caused by obstruction (thrombosis or embolism) of an artery resulting in neurologic damage. "Likewise, we recently reported Plin2 induction and LD biogenesis in microglia after cerebral ischemia." (PMID 37691115, 2023).
cervical cancer (2 papers, 2022 to 2024). A primary or metastatic malignant neoplasm involving the cervix. "After multivariate Cox regression analysis, eight genes were identified as key predictors of HLA-G-driven DEGs in the prognostic risk model for predicting the overall survival of patients with cervical cancer, including CD46, LGALS9, PGM1, SPRY4, CACNB3, PLIN2, MSMO1, and DAGLB." (PMID 35924232, 2022).
glioma (2 papers, 2018 to 2023). A benign or malignant brain and spinal cord tumor that arises from glial cells (astrocytes, oligodendrocytes, ependymal cells). "We explored that PLIN2/3/4/5 were highly expressed in all IDH wild-type gliomas in the CGGA dataset." (PMID 37189627, 2023). "For instance, lncRNA MEG3 promotes the proliferation of glioma cells through targeting Wnt/β-catenin signal pathway;38 lncRNA PLIN2 promotes the development of chronic myelogenous leukemia via the GSK3 and Wnt/β-catenin signaling pathways." (PMID 30166525, 2018). "Our findings suggested that PLIN2 and PLIN3 expression levels were elevated in glioma." (PMID 37189627, 2023). "Therefore, the high expression of PLIN2 and PLIN3 in glioma might be related to the malignant progression of glioma and this needs further exploration." (PMID 37189627, 2023). "Survival analysis showed that PLIN2 and PLIN3 expression did not correlate significantly with the survival prognosis of GBM patients, but was associated with shorter survival in LGG patients, and that PLIN2/PLIN3 overexpression was correlated with the malignant phenotype of gliomas." (PMID 37189627, 2023). "Furthermore, we observed that the expression levels of PLIN2 and PLIN3 were higher in the recurrent tissues than in the primary tumors, indicating that they may play essential roles in the development and recurrence of gliomas." (PMID 37189627, 2023). "mRNA levels of PLIN2 and PLIN3 were not statistically different between grade II and grade III, and the highest mRNA levels of both were expressed in grade IV glioma tissues." (PMID 37189627, 2023).
Hepatic fibrosis (2 papers, 2018 to 2025). The presence of excessive fibrous connective tissue in the liver. "Both clinical trials NCT03524365 (BRAVES) and NCT04677101 (LIBRA) tested perilipin-2 (PLIN2) and a member of RAS oncogene family (RAB14) in circulating monocytes as a prognosticator of histological NASH and liver fibrosis, respectively." (PMID 39796162, 2025).
ischemia (2 papers, 2023 to 2024). A hypoperfusion of the BLOOD through an organ or tissue caused by a PATHOLOGIC CONSTRICTION or obstruction of its BLOOD VESSELS, or an absence of BLOOD CIRCULATION. "We validated the ischemia-induced endothelial upregulation of Plin2 expression at the protein level by immunofluorescence in brain tissue section 1-day post-ischemia." (PMID 37691115, 2023). "Both PLIN2 and iNOS expression gradually decreased to pre‐infarct levels at 28 days post‐ischemia." (PMID 39252446, 2024).
myocardial infarction (2 papers, 2015 to 2019). Gross necrosis of the myocardium, as a result of interruption of the blood supply to the area, as in coronary thrombosis. "Contrary to our expectations, we found that Plin2-deficiency resulted in increased myocardial lipid storage and reduced cardiac function following a myocardial infarction." (PMID 31061399, 2019). "In this study, we found that deficiency in Plin2 resulted in reduced heart function following myocardial infarction." (PMID 31061399, 2019). "Next, we wanted to assess how Plin2-deficient hearts performed under pathological stress and therefore induced a myocardial infarction (induced by ligating the left anterior descending coronary artery)." (PMID 31061399, 2019). "Recently, it was reported that PLIN2 is strongly expressed in macrophages and microglia at the border of organ infarcts, such as in myocardial infarction, as well as in infarcts of the liver, kidney, colon, and brain." (PMID 26367267, 2015). "However, after an induced myocardial infarction, stroke volume and cardiac output were reduced in Plin2−/− mice compared with Plin2+/+ mice." (PMID 31061399, 2019). "Hence, the absence of Plin2 in hearts with a higher workload due to a myocardial infarction may affect the substrate availability and utilization and thereby reduce the heart function." (PMID 31061399, 2019).
pancreatitis (2 papers, 2013 to 2021). Inflammation of the pancreas. "Taking physiological mechanisms into consideration, the inverse association of PLIN2 with lipase raises the question of whether this is due to pancreatitis and its associated multiple organ dysfunction or rather an effect of higher PLIN2 metabolization of serum lipases." (PMID 34572396, 2021).
papillary renal cell carcinoma (2 papers, 2023 to 2024). A rare subtype of renal cell carcinoma, arising from the renal tubular epithelium and showing a papillary growth pattern, which typically manifests with hematuria, flank pain, palpable abdominal mass or nonspecific symptoms, such as fatigue, weight loss or fever. "Their results suggest that aquaporin 1 and perilipin 2 possess high sensitivity and specificity for detecting clear cell and papillary renal cell carcinoma." (PMID 38125591, 2023).
pyometra (2 papers, 2022 to 2025). "This study focuses on lipid metabolism and oxidative stress, revealing the key regulatory role of AMPK and PLIN2 in canine pyometra." (PMID 40082867, 2025). "The phosphorylation of AMPK and the expression of PLIN2 significantly increased in the pyometra group." (PMID 40082867, 2025). "Immunohistochemical analysis showed a significant increase in the expression of p-AMPK and PLIN2 in the myometrium, surface epithelium, and glandular epithelium of pyometra group samples compared to the control group." (PMID 40082867, 2025). "The expression of related lipid synthesis proteins such as ACC1, FASN, SREBP-1c, and PLIN2 was upregulated, while PPARα and PGC1α were downregulated in bitches with pyometra." (PMID 40082867, 2025). "In pyometra specimens, the amount of PLIN2-positive LDs was generally higher compared to healthy samples." (PMID 35689217, 2022). "This study demonstrates that dysregulated lipid metabolism is a critical driver of canine pyometra progression, characterized by coordinated upregulation of ACC1, FASN, SREBP-1c, PLIN2 and suppression of PPARα and PGC1α." (PMID 40082867, 2025). "In our analyses, PLIN2 and PLIN3 were more abundant in pyometra-affected endometrium samples compared to healthy ones." (PMID 35689217, 2022). "Therefore, in canine pyometra, the AMPK/PLIN2 signaling might act as a significant regulatory role for modulating lipid storage and mobilization, optimizing cellular energy utilization, and influencing the regulatory mechanisms of oxidative stress and inflammatory responses." (PMID 40082867, 2025).
sarcoma (2 papers, 2020 to 2023). A usually aggressive malignant neoplasm of the soft tissue or bone. "PLIN1 was absent from non-lipomatous sarcomas (0/179), PLIN2 expressed in all fibrosarcomas (18/18), Ewing's sarcomas (17/17), epithelioid sarcomas (8/8), and in most rhabdomyosarcomas (17/22), leiomyosarcomas (31/42), dermatofibrosarcoma protuberans (23/38), and undifferentiated sarcomas (33/34)." (PMID 32368290, 2020). "PLIN2, PLIN3 and PLIN5 expressions were significantly different among non-lipomatous sarcoma (all P<0.01)." (PMID 32368290, 2020). "Kruskal-Wallis test analysis found that the expressions of PLIN2 (P<0.001), PLIN3 (P<0.001) and PLIN5 (P = 0.013) had a significant difference in various non-lipomatous sarcomas, except for epithelioid sarcomas." (PMID 32368290, 2020). "However, due to the small sample size of epithelioid sarcomas, we analyzed the expression of perilipins in the remaining six sarcomas and found that PLIN2, PLIN3 and PLIN5 showed different and rich expressions in non-lipomatous sarcomas, especially high-grade sarcoma." (PMID 32368290, 2020).
acute kidney injury (1 paper, 2021). Sudden and sustained deterioration of the kidney function characterized by decreased glomerular filtration rate, increased serum creatinine or oliguria. "However, the underlying mechanism of Plin2 in I/R-induced acute kidney injury (AKI) remains elusive." (PMID 34541006, 2021).
acute pancreatitis (1 paper, 2021). An acute inflammatory process that leads to necrosis of the pancreatic parenchyma. "Because serum PLIN2 was strongly negatively correlated with serum lipase and the presence of acute pancreatitis, we investigated whether in the subgroup of patients with acute pancreatitis serum PLIN2 was associated with increased ICU mortality." (PMID 34572396, 2021). "Correspondingly, patients admitted due to acute pancreatitis presented with decreased PLIN2 concentrations." (PMID 34572396, 2021). "However, serum PLIN2 was not able to discriminate a mortality difference in the small subgroup of patients with acute pancreatitis (n = 13)." (PMID 34572396, 2021).
age (1 paper, 2025). A temporal measurement of the time period elapsed since an identifiable point in the life cycle of an organism. "While future studies (e.g., SREBP1/PLIN2 silencing) are needed to confirm a direct causal link between LD regulation and hUC‐MSC function, our findings highlight the therapeutic potential of hUC‐MSCs in age‐related neurodegenerative disorders." (PMID 41078306, 2025).
alcoholic liver diseases (1 paper, 2014). A disorder caused by damage to the liver parenchyma due to alcohol consumption. "Future studies will additionally investigate the role of Plin2 in advanced stages of alcoholic liver disease." (PMID 24831094, 2014).
alcoholic steatohepatitis (1 paper, 2022). "PLIN2 is overexpressed in patients with alcoholic steatohepatitis." (PMID 36685864, 2022).
aneurysm (1 paper, 2023). Bulging or ballooning in an area of an artery secondary to arterial wall weakening. "The remaining 12 aneurysms (63.2%) were made up of 29.8% PLIN2+ MPs." (PMID 37781924, 2023). "In detail, we found 7 aneurysms that were exclusively composed of PLIN2– MPs." (PMID 37781924, 2023).
Anxiety (1 paper, 2019). Intense feelings of nervousness, tension, or panic often arise in response to interpersonal stresses. "Finally, anxiety markers in HFD animals, such as distance traveled in the central zone and entries into the central zone, were strongly negatively correlated with the abundance of Plin2+ cells in close proximity to the LV." (PMID 30612898, 2019).
Aortic dissection (1 paper, 2025). Aortic dissection refers to a tear in the intimal layer of the aorta causing a separation between the intima and the medial layers of the aorta. "The discovery of PLIN2 and PLIN3 as central modulators of lipid metabolism in aortic dissection highlights their potential as both diagnostic biomarkers and intervention targets." (PMID 41246346, 2025). "The upregulation of PLIN2 and its specific expression in macrophages were further confirmed in an Ang II-induced aortic dissection mouse model." (PMID 41246346, 2025).
Ascites (1 paper, 2025). Accumulation of fluid in the peritoneal cavity (between the layers of the peritoneum that lines the abdomen). "Critically, suppression of PLIN2 led to significant attenuation in vascular permeability and ascites development when compared to the control group." (PMID 39921309, 2025).
bladder cancer (1 paper, 2017). "Previous analysis of human bladder cancer specimens identified a correlation between the presence of RXRAS427F/Y and both the up-regulation of PLIN2 expression and PPAR signaling pathway activity." (PMID 29143738, 2017).
cardiac hypertrophy (1 paper, 2022). "This indicates that at least under physiological conditions, a decline in PPARα decreases cardiac Plin2 without inducing protein oxidation or cardiac hypertrophy." (PMID 35259201, 2022).
carotid atherosclerosis (1 paper, 2013). A thickening and loss of elasticity of the walls of carotid arteries that occur with formation of atherosclerotic plaques. "Adipophilin (perilipin 2) has recently been established as a sensitive marker of monocyte lipid loading and that its protein expression is increased in symptomatic carotid atherosclerosis." (PMID 23658787, 2013).
cholestasis (1 paper, 2020). Impairment of the bile flow caused by obstruction within the liver, or outside the liver in the bile duct system. "Here our study showed a reduction of PLIN2 both in vivo and in vitro suggesting a role of cholestasis mediated regulation on PLIN2 expression." (PMID 32612285, 2020). "Similarly, our cell culture models of cholestasis demonstrated increased activation of AMPK and CREB along with downregulation of FASN and PLIN2 in HepG2 cells, emphasizing the possible role of bile acid in lipid metabolism during cholestatic liver injury." (PMID 32612285, 2020).
cutaneous melanoma (1 paper, 2022). A primary melanoma arising from atypical melanocytes in the skin. "In cutaneous melanomas, high PLIN2 expression was associated with poor metastasis-free survival (MFS), disease-free survival (DFS), and overall survival (OS) rates of patients." (PMID 35372038, 2022).
demyelinating disease (1 paper, 2025). A broad group of disorders that affect the myelin sheaths that cover the neurons. "PLIN2 deficiency reduced inflammation signals and accelerated remyelination, providing new insight into the treatment of demyelinating disease with LDs accumulation." (PMID 40862760, 2025). "PLIN2, a surface marker of LDs highly expressed in lipid-laden microglia/macrophages in many demyelination diseases, helps LDs escape from degradation, which impairs the remyelination process." (PMID 40862760, 2025).
dysplasia (1 paper, 2021). A usually neoplastic transformation of the cell, associated with altered architectural tissue patterns. "Reinforcing the LD regulation throughout EAC development, an association between PLIN-2 expression and the presence of dysplasia was detected in BE patients." (PMID 33441691, 2021). "Association analysis between BE, EAC and ESCC patients clinico-pathological data and PLIN2 protein expression was performed revealing a statistically significant association between PLIN2 expression and the presence of dysplasia in BE patients." (PMID 33441691, 2021).
Hypoglycemia (1 paper, 2020). A decreased concentration of glucose in the blood. "While HAUS6 and its nearby genes RRAGA and PLIN2 have various cancers (including PrCa) as associated diseases in Open Targets Genetics, one or more of them are related to metabolism phenotype, abnormal gluconeogenesis and hypoglycemia in mice." (PMID 33290408, 2020).
IgA nephropathy (1 paper, 2022). "Perilipin-2 expression was detectable in glomeruli of healthy subjects and in IgA nephropathy and membranous nephropathy disease controls." (PMID 36613637, 2022). "Kidney biopsies from patients with FSGS, whose plasma induced perilipin-2 expression and lipid droplet formation in hPod (rec1 and nat1), were stained with anti-perilipin-2 antibody and compared to a healthy kidney and biopsies from patients with IgA nephropathy or membranous nephropathy." (PMID 36613637, 2022).
insulinoma (1 paper, 2017). "Exposure of MIN6, a mouse insulinoma cell line, to oleic acid (OA) or palmitic acid (PA) increased PLIN2 expression in these cells." (PMID 28102311, 2017).